MTOR (mechanistic target of rapamycin kinase)
Diseases named in the same sentence as MTOR in open-access papers (continued):
Sharing a sentence is not in itself a finding about the gene and the disease.
cancer (continued). "Other ligands mentioned can further be evaluated by various in vitro and in vivo studies in various types of cancer which involves PI3K/mTOR pathway." (PMID 36244040, 2023). "The biochemical mechanisms that outline the development of cancer in states of metabolic imbalance are growing, with the mTOR signaling pathway and hormones such as leptin serving as scaffolds for pharmacological intervention." (PMID 37626871, 2023). "The focal adhesion kinase inhibitor BI853520 inhibits the proliferation, migration, invasion and epithelial-mesenchymal transition of cancer cells by affecting the PI3K/AKT/mTOR signaling pathway." (PMID 36891150, 2023). "The outcomes revealed substantial enrichment of the DDX52 gene across various pathways, notably the cell cycle, DNA replication, ERBB, MAPK, mTOR, cancer pathways, TGF-beta, and Wnt." (PMID 37833424, 2023). "mTOR signaling is dysregulated in cancer cells, while T cell function requires upregulation of mTOR." (PMID 37274280, 2023). "Studies using the same cancer model highlighted that the inhibition of mTOR by RADOO1, an analog of rapamycin, induced an overexpression of PD-L1." (PMID 37834467, 2023). "Efflux transporters, such as p-glycoprotein, can pump mTOR inhibitors out of the cancer cells, reducing drug accumulation and efficacy." (PMID 37834408, 2023). "Comprehensive analysis of the altered phosphoproteins using ROMA software revealed up-regulation of several cancer hallmark pathways such as MAPK, mTOR and integrin/ILK/actin, affecting epithelial and stromal colonic cells." (PMID 37696912, 2023). "mTOR inhibition is an attractive therapeutic target in cancer due to its intervention in cellular functions such as cell survival or cell death, synthesis of biomolecules, and cell migration." (PMID 37223676, 2023). "PI3K/AKT/mTOR pathway is aberrantly activated during tumorigenesis and significantly affects malignant phenotypes of cancer cells, as well as chemotherapy resistance." (PMID 35789211, 2023). "Further research revealed that mTOR is generally activated in neoplasms and controls cancer cell metabolism by regulating key metabolic enzymes; thus, it has been targeted for cancer treatment." (PMID 37784141, 2023). "The PI3K/AKT/mTOR signaling pathway is frequently dysregulated in different types of cancer, including hematologic malignancies." (PMID 37658623, 2023). "Early cancer treatment with dactolisib (dual PI3K/mTOR inhibitor) prevented the development of UBE2C-induced leptomeningeal metastases." (PMID 37215954, 2023). "The PI3K/AKT pathway can be abnormally triggered in a wide range of cancers due to a plethora of mechanisms including somatic mutations and germline mutations in PIK3CA, AKT, PTEN and mTOR genes." (PMID 36765661, 2023). "VitD has been suggested to regulate several pathways including the cancer-relevant mTOR/PI3K-Akt pathways." (PMID 36902107, 2023). "Although the PI3K/AKT/mTOR axis is a target for cancers, the current use of small molecule inhibitors against this axis is limited by the development of drug resistance in patients." (PMID 37569713, 2023). "Drugs known to repress HIF-1α expression indirectly, such as mTOR inhibitors, can also be used as adjuvant therapy for cancer because it has been shown in preclinical models of HCC that such treatment can suppress tumor growth." (PMID 37240068, 2023). "mTOR also controls autophagy, which is enhanced in cancer, and has been considered a counterbalance to programed cell death, which allows cancerous cells to resist cell death." (PMID 37110415, 2023). "The ERK pathway, another frequently altered pathway in cancer, has common inputs with mTOR and has been shown to produce compensatory effects upon mTOR inhibition." (PMID 37894790, 2023). "A large number of studies have shown that the PI3K/AKT/mTOR signalling pathway can regulate apoptosis, anti-inflammation, anti-cancer and other biological processes." (PMID 36771204, 2023).
cancer (continued). "Dual inhibition of MEK and mTOR effectively suppresses tumor growth and metastasis in this subtype of cancer in vivo." (PMID 38124228, 2023). "In an animal model, inhibition of signaling, including the mTOR pathway, and induction of cancer cell death by increasing expression of the proapoptotic gene Bax and activation of caspase 3/9 have been reported." (PMID 37960338, 2023). "It has been reported that high levels of cholesterol synthesis result in the upregulation of acetyl-coenzyme A acetyl transferase 1 (ACAT1), which induces cancer cell proliferation through the activation of the PI3K/mTOR pathway." (PMID 37754524, 2023). "The main negative regulator of autophagy is PI3K/AKT/mTOR signaling, and potential stimulators in normal and cancer cells include sirtuin 1 (SIRT1) and 5′ adenosine-monophosphate-activated protein kinase (AMPK)." (PMID 36835075, 2023). "PI3K/Akt/mTOR signaling acts as a pro-survival mechanism for cancer cells and is found to be overexpressed in several types of cancer." (PMID 37047624, 2023). "The global ribosome profiling was performed to unravel the mechanism of translation that regulates gene expression through mTOR in cancers." (PMID 37779156, 2023). "mTOR is frequently abnormally expressed and mTOR signaling activation has been identified in cancer." (PMID 36594084, 2023). "Subsequent studies have shown that PD-L1 can activate the internal signals of cancer cells independently of PD-1 and promote the proliferation and survival of cancer cells by inhibiting autophagy and mammalian target of rapamycin (mTOR) activation." (PMID 36810034, 2023). "The PI3K/AKT/mTOR pathway is an intracellular signaling pathway important in regulating the cell cycle, cellular quiescence, proliferation, cancer, and longevity." (PMID 37298208, 2023). "Increased mTOR activation, along with upregulation of respective upstream and downstream signaling components, have been established as oncogenic features in cancer cells in various tumor types." (PMID 37566093, 2023). "In recent years cancer biologists have shifted the focus to developing mTOR-based combination therapies." (PMID 37513916, 2023). "FBXW7, as a ubiquitin ligase, can combine with lots of cancer-related factors, including c-Myc, cyclin E and mTOR." (PMID 37404825, 2023). "Blocking the PI3K/AKT/mTOR pathway has been widely recognized as an attractive cancer therapeutic strategy owing to its crucial role in cell growth and survival." (PMID 37298753, 2023). "At the cellular level, the pathogenesis of AD and cancer both involve the phosphoinositide 3-kinase/protein kinase B/mammalian target of rapamycin (PI3K/AKT/mTOR) signaling pathway, which regulates cell proliferation, metabolism, growth, and autophagy." (PMID 37601068, 2023). "The PI3K/Akt/mTOR pathway is involved in the regulation of cancer cell survival, proliferation, growth, and metabolism." (PMID 37958610, 2023). "Many studies aim to understand the potential resistance mechanisms of mTOR-targeted therapies, which is necessary for the rational application of mTOR inhibitors for the effective treatment of cancer." (PMID 38057772, 2023). "One paper reviewed the regulatory mechanisms of mTORC1 and ferroptosis and proposed co-targeting mTOR and ferroptosis as a potential strategy for cancer treatment." (PMID 37958383, 2023). "The pharmacological inhibition of PI3K, AKT, or mTOR has exerted similar anti-cancer effects in xenograft models of HCC." (PMID 37631344, 2023). "Lysosomal activity is regulated via mTORC1, but activation of the PI3K/AKT/mTOR pathway in many cancers suggests a decline in lysosomal function." (PMID 36819180, 2023).
cancer (continued). "In such cancer cells, the nutritional uptake of neutral and essential neutral amino acids, and co-regulation of the mammalian target of rapamycin (mTOR) signaling pathway is mediated by the LAT1 transporter." (PMID 36895635, 2023). "The genome location of GOLPH3 (chr5p13) is frequently amplificated in many cancers; GOLPH3 protein modulates cell size, promotes growth-factor-induced mTOR signaling in human cancer cells, and changes the response to an mTOR inhibitor rapamycin in vivo." (PMID 36967990, 2023). "The PI3K/AKT/mTOR pathway is commonly dysregulated in human cancer, due to mutation of dominantly acting oncogenes (PIK3CA, AKT isoforms, MTOR), inactivation of tumor suppressor genes (PTEN, TSC1, TSC2, PIK3R1), and amplification of growth-promoting oncogenes." (PMID 37909334, 2023). "In turn, SREBP1 is controlled by activation of mammalian target of rapamycin (mTOR), one of the major signaling nodes in cancer." (PMID 37444561, 2023). "The mTOR signalling pathway also plays a crucial role in the tumour microenvironment, and in the interaction between cancer cells and the tumour microenvironment, where it regulates angiogenesis, metabolism and modulates the immune response." (PMID 36980746, 2023). "Given the centrifugal expansion of tumour tissue, mTOR expression is expected to be more intense at the edge of cancer, where the proliferation is more significant." (PMID 37366904, 2023). "The primary focus switched to anti-cancer therapy as a result of the significant function of mTOR in cell growth and metabolism, and temsirolimus (CCI-779) was licenced for the treatment of renal cell carcinoma in 2007." (PMID 36826066, 2023). "In another way, like many other cancers, the PI3K/Akt/mTOR pathway was also confirmed to be dysregulated and associated with aggressive tumor behaviors and poor prognosis in RCC." (PMID 38093375, 2023). "The activation of the mTOR pathway results in drug resistance in many cancers, inducing breast cancer resisted to trastuzumab, tamoxifen and endocrine therapy, prostate cancer resisted to vincristine, and ovarian cancer resisted to cisplatin." (PMID 36998461, 2023). "Metformin inhibits mitochondrial complex I and triggers energy depletion, which activates AMPK and inhibits mTOR, restraining cancer growth via the maintenance of energy homeostasis." (PMID 37344841, 2023). "MET targets the mTOR pathway in cancer cells, and WZB117 targets BCL2 to alter GLUT1 at the cancer site." (PMID 36850263, 2023). "Oncogenic signaling transduction pathways, including the phosphoinositide 3-kinase (PI3K), AKT, and mammalian target of rapamycin (mTOR) pathways, enhance the Warburg effect in tumors, facilitating cancer cell growth and metastasis." (PMID 36768977, 2023). "During glucose metabolism, activation of mTOR signaling in cancer cells can enhance the expression of genes related to glucose uptake and glycolysis through upregulation of the hypoxia-inducible factor 1α (HIF1α)." (PMID 37259304, 2023). "The PI3K/AKT/mammalian target of rapamycin (mTOR) pathway hyperactivity is correlated with tumor progression in a wide variety of cancers." (PMID 38137424, 2023). "PIK3CA mutations are frequently observed in a variety of cancers, including breast, colorectal, and ovarian cancer, and result in the activation of the PI3K/AKT/mTOR cascade." (PMID 37779156, 2023). "FNDC1 - Fibronectin type III domain containing 1 (FNDC1) activates a G-protein signaling cascade that leads to the activation of PI3K/Akt/mToR signaling which leads to cancer growth and proliferation." (PMID 38304289, 2023). "A PI3K inhibitor (LY294002) was found to inhibit mTOR, slow disease progression, eliminate lung metastasis and prolong the survival time in mice due to inhibition of cancer growth and proliferation, increased apoptosis, and decreased cell activity." (PMID 37853445, 2023).
cancer (continued). "We employed an AI method to identify a potent and selective mTOR inhibitor and validated this compound’s anti-cancer and pro-longevity effects in cell culture and C. elegans models." (PMID 37175557, 2023). "Blocking mTOR creates a starvation-like effect in cancer cells, interfering with cell growth, division, metabolism, and angiogenesis." (PMID 37240915, 2023). "The mTOR signaling pathway regulates multiple major cellular life processes and is also involved in many pathological conditions, including cancer." (PMID 37637052, 2023). "Sapanisertib (MLN0128) is a new type of mTOR inhibitor that has previously been shown to have anti-tumor activity in other cancer patients." (PMID 37007127, 2023). "AMPK activation and mTOR inhibition have been referred as ‘hallmarks of metformin treatment’ in cancer." (PMID 36781298, 2023). "Rapamycin was the first mTOR inhibitor to be identified, initially being proposed as an antifungal antibiotic, but has since been studied in the context of cancer treatment." (PMID 36900235, 2023). "Abnormalities in the PI3K/AKT/mTOR signaling pathway are very prevalent in malignant tumors and mutations in PIK3CA have been frequently detected in many cancers including OCCC, reportedly at 40%." (PMID 37270486, 2023). "Activating the mTOR pathway mediated various cancer features, including angiogenesis and cell proliferation." (PMID 37512149, 2023). "For example, the ROS/PI3K/Akt/mTOR signaling pathway is involved in both neurogenesis and cancer progression." (PMID 37566075, 2023). "Cell signaling through the phosphatidylinositol-3-kinase (PI3K)/AKT/mammalian target of rapamycin (mTOR) is one of the most central intracellular pathways in cancer." (PMID 36911757, 2023). "The phosphatidylinositol-3-kinase (PI3K)-Akt-mTOR signaling pathway is a core pathway in many forms of human cancers, in which it is usually activated at abnormal levels." (PMID 37283744, 2023). "The mTOR related PI3K/Akt/mTOR signaling pathway provides a theoretical basis for mTOR-targeted therapy in cancer." (PMID 36809979, 2023). "Everolimus, an inhibitor of mTOR, is a medication used as an immunosuppressant and as a target therapy for many different cancers." (PMID 37046450, 2023). "Conversely, mammalian target of rapamycin (mTOR) inhibitors, such as sirolimus, reduce the incidence of cancer by suppressing p70 S6K, interleukin-10, and cyclin; downregulating VEGF; and inducing apoptosis." (PMID 38269025, 2023). "Some mechanisms of the mTOR signaling pathway in the occurrence and development of cancer have been studied to some extent." (PMID 37637052, 2023). "Similar to other nutrient sensing mechanisms, such as the AMP-activated protein kinase (AMPK) pathway and mammalian target of rapamycin (mTOR) pathway, dysregulation of the HBP is strongly associated with cancer." (PMID 37838167, 2023). "Consistent with the findings of this study, PPP2R1A is frequently mutated in OCCCs, thus offering the therapeutic advantage of targeting the PI3K/AKT/mTOR pathway in this cancer type." (PMID 37627318, 2023). "MET activates AMPK and downregulates mTOR in tumor cells, which reduces protein and lipid synthesis and restricts cancer cell growth and proliferation MET is a powerful anticancer agent that inhibits cell proliferation and induces apoptosis." (PMID 36850263, 2023). "In this context, given the genetic alterations in PI3K/AKT/mTOR pathway that characterize EAOCs, the potential for mTOR signaling to serve as a therapeutic target in this cancer type has been further studied." (PMID 37627318, 2023). "The fact that activated mTOR signaling has been related to cancer generated substantial interest in pharmacologic targeting of this pathway for cancer treatment." (PMID 36816923, 2023).
cancer (continued). "The glycolytic enzyme ENO1 is reported to be overexpressed in cancer and inflammatory cells and this promotes glycolysis, activates signalling pathways important in cancer including PI3K/AKT/mTOR, and drives tumor migration, invasion, and metastasis." (PMID 36564470, 2023). "Activating mutations in key factors of the PI3K/AKT/mTOR pathway, such as TIE2, PIK3CA, AKT, or MAP3K3, lead to the activation of PI3K signaling and uncontrolled cell proliferation in many human cancers." (PMID 37109059, 2023). "STK11, also named LKB1, controls the activity of AMP-activated protein kinase (AMPK) by phosphorylation and downregulates mTOR signaling, thereby inhibiting cancer cell proliferation and protein synthesis." (PMID 37351538, 2023). "TGF-β signaling pathway, mTOR signaling pathway and pathway in cancer are common tumor-associated signaling pathways, including in GC." (PMID 37404478, 2023). "Keeping in view the role of this important signalling cascade in crucial stages of cancer development, this review is aimed at highlighting the regulation of mTOR signalling pathway and its involvement in tumourigenesis." (PMID 37513916, 2023). "EC cells frequently show overactivation of PI3K/mTOR (∼50% of EC cells harbour a double allelic mutated PTEN gene) and canonical NF-kB pathways, which protect cancer cells from TRAIL-induced apoptosis." (PMID 37919293, 2023). "Dysregulation of the mTOR signaling pathway is involved in multiple human diseases including cancer, and vast reports have verified that the activation of mTOR participates the progression and chemoresistance of PDAC." (PMID 37626304, 2023). "Previous studies have shown that modulation of mTOR activity in combination with doxorubicin shows synergistic activity in in vitro and in vivo models of various cancers." (PMID 36901842, 2023). "PIK3CA and AKT1/2 are two of the main members of the PI3K/AKT/mTOR signalling pathway, which is often activated in a range of cancers and contributes to their development." (PMID 37352361, 2023). "Recent studies proposed that the mTOR/AKT pathways are the ones mainly mediating the intrinsic activities of PD-L1 in several cancer systems." (PMID 37830552, 2023). "There is evidence that phosphorylation of AKT and mTOR affects copper-induced disease progression in a variety of diseases, including cancer." (PMID 36909185, 2023). "Uncontrolled ROS generation drives cancer progression through multiple signaling pathways such as mTOR, PTEN, and MMPs." (PMID 37204251, 2023). "We previously reported that CGs induce cell cycle arrest by attenuating MAPK, PI3K/AKT/mTOR signaling pathways in cancer cells." (PMID 37958905, 2023). "It is an allosteric inhibitor of mTOR, a protein kinase known to be dysregulated in cancer and metabolic disorders." (PMID 37370314, 2023). "A new study revealed a novel mechanism of the PI3K/AKT/mTOR/SREBP1 signaling pathway that protects cancer cells by inhibiting ferroptosis (an iron-dependent form of cell death caused by the accumulation of phospholipid peroxides)." (PMID 36969840, 2023). "On the other hand, increasing glucose levels activate SIK3/mammalian target of rapamycin (mTOR) activity, which augments cancer cell proliferation and aerobic glycolysis." (PMID 36731029, 2023). "The mTOR axis is dysregulated in many cancer cells, thus representing a promising target in anti-cancer therapy." (PMID 37237490, 2023). "In line with this view, here we showed that SMYD3 is part of a multiprotein complex comprising AMPK and mTOR in cancer cells exposed to DNA-damaging drugs." (PMID 37998381, 2023). "The mTOR pathway regulates metabolism and thus the functions of numerous intra-tumor inflammatory cells and cancer cells." (PMID 37190322, 2023). "It is upregulated in various types of tumors, acting in cancer progression by mTOR signaling pathway." (PMID 37190332, 2023). "Expression of key lipogenic enzymes, including FASN, is often regulated by the mTOR-SREBP1 axis in cancer cells." (PMID 37444561, 2023).